CD34 (CD34 molecule)
Diseases named in the same sentence as CD34 in open-access papers (continued):
Sharing a sentence is not in itself a finding about the gene and the disease.
teratoma (9 papers, 2013 to 2024). A non-seminomatous germ cell tumor characterized by the presence of various tissues which correspond to the different germinal layers (endoderm, mesoderm, and ectoderm). "In one such study, CD34+ cells isolated from teratomas displayed myeloid-biased MLE with 1 × 104 CD34+ teratoma cells yielding approximately 2.5% human cells in the bone marrow of immune-deficient mice." (PMID 39223325, 2024). "Hematopoietic progenitors (HPCs) stained with both human CD45 and human CD34 were isolated from the teratoma and BM cells using a FACS Aria Cell Sorter." (PMID 30367142, 2018). "Subsequently, 1 × 104 human CD45+ CD34+ HPCs harvested from the teratoma were injected into the bone marrows of irradiated NSG mice (2 Gy)." (PMID 30367142, 2018). "Flow cytometric analysis using dissociated teratoma tissues also revealed the presence of human CD45+ CD34+ HPC fractions." (PMID 30367142, 2018). "However, the percentages of CD34+ cells obtained from the teratomas were below 0.1 % in both studies." (PMID 27686241, 2016). "Whereas relative lower expression level of tumorigenesis genes Eno2, Nes, CD34 and Afp in Mst-/- EBs than wild type EBs may be one of the reasons that Mst-/- ES cells cannot grow teratoma." (PMID 24224013, 2013). "Human teratomas that developed in the RAG2 knockout SCID pigs also had a higher prevalence of CD45+ and CD34+ cells in the teratoma than in SCID mice." (PMID 30560086, 2018). "Moreover, in the BM cells of teratoma-bearing mice, human CD45 + CMML cells were detected, which were few CD34 + andCD14 + monocytes." (PMID 30367142, 2018). "We tested this approach in the present work and found that survivin inhibitor YM155 did spare CD34+ cord blood cells, did not affect their engraftment properties, and completely eradicated in vivo teratoma formation from i.v. injected hiPSCs." (PMID 28191782, 2017). "Our previous study showed that CD34/CD73 double-positive cells in the testis have high proliferation capacity and can differentiate into three germ layer lineages, without forming teratomas." (PMID 34165777, 2021).
acute B lymphoblastic leukemia (8 papers, 2012 to 2025). "In B-cell precursor acute lymphoblastic leukemia in children, the presence of CD34+CD38− lymphoblasts at the diagnosis may be considered an unfavorable prognostic factor for disease recurrence." (PMID 37675394, 2023).
Alzheimer disease (8 papers, 2011 to 2026). A progressive, neurodegenerative disease characterized by loss of function and death of nerve cells in several areas of the brain leading to loss of cognitive function such as memory and language. "Peaks from CD34+/monocyte-derived brain myeloid cells showed preferential enrichment for risk loci associated with multiple sclerosis, Alzheimer’s disease, intellectual disability, and depression in comparison to iHPCs peaks." (PMID 41256000, 2025). "Here, we investigated the therapeutic effects of a defined combination of unmanipulated MSCs and CD34+ HSCs, termed Neuro-Cells (NC), in a murine model of Alzheimer’s disease (AD), the APPswe/PS1dE9 mouse." (PMID 40862772, 2025). "This systematic review aimed to evaluate the presence and number of CD34+ cells in individuals with Alzheimer’s disease (AD) to better understand the role of vascular factors in the pathogenesis of neurodegenerative conditions." (PMID 39997032, 2025). "In this review, we aim to differentially evaluate the presence and number of CD34+ cells in individuals afflicted with Alzheimer’s disease." (PMID 39997032, 2025). "It presents data on the effectiveness of using comprehensive panels of molecular biomarkers in clinical practice, including β-amyloid, CD34, claudin, DRP1, endothelin-1, NF-kB, PINK1, RAGE, S100, α-synuclein, and tau protein, in patients with Alzheimer’s disease (AD) and vascular dementia (VD)." (PMID 41516246, 2025).
chronic lymphocytic leukemia (8 papers, 2013 to 2025). "Peripheral blood from 64 dogs with CD34+ AL, 10 with B cell chronic lymphocytic leukaemia (CLL), and 10 healthy controls were prospectively evaluated for ALP enzymatic activity via cytochemical staining; a subset also underwent ALP detection by flow cytometry (FC)." (PMID 41137732, 2025).
colitis (8 papers, 2012 to 2024). Inflammation of the colon. "The fate of the CD34+ fibro seven and Gli1+ fibro 13 subsets are less clear in this murine model of colitis." (PMID 39872845, 2024). "In both acute and chronic DSS colitis murine models, CD34+GP38+α-SMA- pericryptal telocytes have been shown to facilitate intestinal healing and repair through expression of GREM1." (PMID 39872845, 2024). "Here, we show that treatment with LD IL-2 reduced 2,4,6-trinitrobenzensulfonic acid (TNBS) colitis severity in NOD.PrkdcscidIl2rg-/- (NSG) mice reconstituted with human CD34+ hematopoietic stem cells." (PMID 33717161, 2021). "During colitis, the expression of lymphocyte survival/proliferation factor IL-7 and chemokine CCL19 persists in PDFGRαlow CD34+ cells at the chronic phase, which contributes to induction of the prolonged survival of T cells." (PMID 39327633, 2024). "In this T cell independent model of colitis, blockade of IFN-γ diminished LSK increases in the BM and spleen, as well as CD34− LT-HSC and CD150+ LT-HSC increases in the BM (data not shown)." (PMID 23200826, 2012). "PDFGRαlow CD34+ cells transiently increase expression of the adhesion molecule VCAM-1 as well as the inflammatory mediators CCL2 and Csf1 at the acute phase of dextran sodium sulfate-induced colitis in mice, which attracts immune cells to the mucosa." (PMID 39327633, 2024). "In another study with murine dextran sulphate sodium (DSS)-induced colitis, exogenous CD34-negative stem cells also migrated towards the inflamed colon and differentiated into endothelial cells following intravenous administration." (PMID 22432015, 2012). "In contrast, Cd101 and Cd34, which may serve as markers for Type 2 eosinophils were upregulated in eosinophils from asthmatic mice but not in eosinophils from mice with colonic inflammation." (PMID 34970274, 2021). "One limitation of this study is that we have only studied the transgenic mice using the TNBS model, a T cell-driven colitis model resembling human CD34, but other experimental colitis models that are also commonly used in IBD research have not been tested for the RenTg mice." (PMID 27271344, 2016).
dilated cardiomyopathy (8 papers, 2012 to 2025). Cardiomyopathy which is characterized by dilation and contractile dysfunction of the left and right ventricles. "The underlying mechanism of how mobilized CD34+ contribute to improvement of cardiac remodeling in pediatric dilated cardiomyopathy patients remains to be elucidated." (PMID 23150834, 2012). "The recently completed repetitive intramyocardial CD34+ cell therapy in dilated cardiomyopathy study (REMEDIUM study) evaluated the potential benefits of repetitive transendocardial CD34+ cell therapy in DCMP patients." (PMID 36547426, 2022). "Similarly, in a study of 55 dilated cardiomyopathy patients randomized to CD34+ cell transplantation or control, the treated group experienced a significant increase in % EF and exercise capacity, as well as reduced NT-proBNP and mortality rates." (PMID 40723901, 2025). "These are similar to our results and support the treatment of ischemic and non-ischemic dilated cardiomyopathies with autologous CD34+ cells." (PMID 37880753, 2023).
Ewing sarcoma (8 papers, 2009 to 2025). A small round cell tumor that lacks morphologic, immunohistochemical, and electron microscopic evidence of neuroectodermal differentiation. "We found significantly more lung metastases present in the orthotopic hu-CD34+ mice harboring TC32 Ewing sarcoma tumors as compared with NSG mice harboring TC32 Ewing sarcoma tumors." (PMID 40858520, 2025). "Ewing sarcoma tumors were established in the hu-CD34+ model and mice were treated in one of four groups: (i) vehicle control and no radiotherapy, (ii) vehicle control and radiotherapy, (iii) RER and no radiotherapy, and (iv) RER and radiotherapy." (PMID 40858520, 2025). "Our data clearly demonstrate transcriptional signature differences between identical Ewing sarcoma developed in hu-CD34+ versus NSG mice, thus highlighting the influence of immune cells on Ewing sarcoma tumor biology." (PMID 40858520, 2025). "We then utilize an in vivo, immunocompetent humanized (hu-CD34+) mouse model to demonstrate that TGFβ inhibition enhances total immune cell infiltration and reduces lung metastases following radiotherapy in Ewing sarcoma." (PMID 40858520, 2025). "To investigate the role of TGFβ inhibition in modulating the Ewing sarcoma immune microenvironment following radiotherapy, we tested the ability of RER, a trivalent ligand trap for TGFβ, to inhibit TGFβ in our hu-CD34+ Ewing sarcoma model." (PMID 40858520, 2025). "Unsupervised clustering of the transcriptional profiles across all samples indicated that Ewing tumors developed in the hu-CD34+ and immunodeficient NSG models cluster separately." (PMID 40858520, 2025). "Having established a hu-CD34+ Ewing sarcoma model, we next sought to understand the transcriptomic and biological differences noted in Ewing tumors established in hu-CD34+ versus NSG (immunodeficient) mice." (PMID 40858520, 2025). "The findings on comet assay and γ-H2AX expression suggest that BO-1055 induces far less DNA double strand breaks in hMSC and CD34+ hematopoietic cells when compared to A673 Ewing sarcoma cells." (PMID 27248664, 2016). "Our RT-PCR analysis confirmed that Ewing's sarcoma cells expressed higher levels of HDGF with respect to putative normal controls (CD34 positive cells and normal muscle tissues)." (PMID 19144156, 2009). "Upregulated gene transcripts in Ewing sarcoma tumors developed in the hu-CD34+ models compared with the NSG model include Wnt3, Hox gene family members, and collagen family genes, some of which have been previously reported to be pro-tumorigenic in Ewing sarcoma." (PMID 40858520, 2025). "Transcriptional data underwent unsupervised clustering and demonstrated that transcriptional profiles of Ewing sarcomas treated with radiotherapy and developed in the hu-CD34+ model cluster separately from Ewing sarcoma treated with radiotherapy and developed in immunodeficient mice." (PMID 40858520, 2025). "We developed and utilized a CD34+ humanized mouse model of Ewing sarcoma (human immune cells plus human tumor cells) to study the impact of TGFβ inhibition, utilizing a TGFβ trap, on Ewing sarcoma biology." (PMID 40858520, 2025). "The observation that treatment with NOA2 led to an accumulation of hCD45+ and hCD33+ immune cells in Ewing tumors in the PBL-NSG mouse study above led us to perform a second treatment study in CD34+ HSC-reconstituted NSG-SGM3 mice which show enhanced engraftment of human myeloid cells." (PMID 38534214, 2024). "As a next step toward elucidating the functional role of TGFβ in the Ewing sarcoma TME, we developed and validated an immunocompetent mouse model of Ewing sarcoma utilizing hu-CD34+ humanized mice." (PMID 40858520, 2025). "Tumors were established in both the hu-CD34+ immunocompetent mouse model and an NSG immunodeficient murine model utilizing the human TC32 Ewing sarcoma cell line." (PMID 40858520, 2025).
Ewing sarcoma (continued). "There are no robust syngeneic or transgenic mouse models of Ewing sarcoma, so for this study, we developed a humanized mouse model of Ewing sarcoma utilizing a hu-CD34+ model to be able to ask specific questions about how radiotherapy and TGFβ inhibition affect the tumor immune response." (PMID 40858520, 2025). "To further analyze radiotherapy-induced transcriptional changes in an immunocompetent model of Ewing sarcoma, we identified 22 overlapping genes that were differentially expressed following radiotherapy in tumors developed from both TC32 and A673 cell lines in hu-CD34+ mice." (PMID 40858520, 2025). "Second, utilizing our hu-CD34+ orthotopic mouse model of Ewing sarcoma, we demonstrate that combining TGFβ inhibition with radiotherapy results in increased total immune cell (CD45+) infiltration into Ewing sarcomas in comparison with no treatment." (PMID 40858520, 2025).
fibrosis (8 papers, 2015 to 2025). the formation of excess fibrous connective tissue in an organ or tissue in a reparative or reactive process. "The literature indicates that the surface antigens CD90 and CD34 correlate and are associated with increasing fibrosis of the skin and mRSS." (PMID 34833021, 2021). "HSCs attraction to the lungs with fibrosis is preceded by a consecutive increase of the quantity of Lin-Sca-1+c-Kit+CD34- -cells, Lin-Sca-1+c-Kit+CD34+-cells, Lin-Sca-1+c-kit+-cells (1st day) and neutrophil leucocytes in bone marrow (3rd day)." (PMID 25927611, 2015).
hemangioendothelioma (8 papers, 2010 to 2025). A vascular proliferation characterized by the presence of prominent endothelial cells and the formation of vascular channels. "Immunohistochemically, hemangioendothelioma cells are positive for CD34, CD31, and vonWillebrand factor." (PMID 34757619, 2023). "An immunohistochemical panel including FKBP12 combined with CD34 and CD31 allows a 93% diagnostic sensitivity of hemangioendothelioma." (PMID 25924932, 2015). "In order to exlude hemangioendothelioma from the differential diagnosis, expression of endothelial markers such as CD34 and CD31 should be performed during the immunohistochemical analysis." (PMID 20205819, 2010). "CD34 expression is usually negative in pseudomyogenic hemangioendothelioma, however a report indicates that it was positive in some cases." (PMID 26315812, 2015). "Endothelial differentiation may be implied in 50% of cases by CD31 expression, however there is a lack of CD34 expression which is not seen in other types of hemangioendothelioma." (PMID 40386009, 2025). "The lack of CD34 and ERG immunopositivity in conjunction with the histological appearance ruled out hemangioendothelioma." (PMID 26187280, 2015).
inflammatory myofibroblastic tumor (8 papers, 2019 to 2025). A multinodular intermediate fibroblastic neoplasm that arises from soft tissue or viscera, in children and young adults. "The histological differential diagnosis of CMN includes metanephric stromal tumor (CD34 positive), stromal type Wilms tumor (WT-1 positive), and inflammatory myofibroblastic tumor (ALK-positive), all of which were negative in our case." (PMID 39493139, 2024). "Negative results for DOG-1, CD117 (KIT), CD34, S-100 protein, neurofilament, cytokeratin, epithelial membrane antigen (EMA), and ALK suggest that PF is a distinct disease entity from GIST, angiomyxoma, neurogenic tumor, sarcomatoid carcinoma, and inflammatory myofibroblastic tumor." (PMID 31360694, 2019).
invasive ductal carcinoma (8 papers, 2011 to 2026). "We found a loss of stromal expression of CD34 with the appearance of a myofibroblastic reaction in almost 100% cases of invasive ductal carcinoma." (PMID 25011545, 2014). "SPARC protein expression was significantly associated with interstitial remodeling, the loss of CD34, and α-SMA expression in invasive ductal carcinoma and interfered with TGF-β1 signaling, which allowed it to play a role in tumor progression." (PMID 35211625, 2022). "We carried out an immunohistochemical study of CD34, SMA, TGF-ß and TGF-ß R1 on a series of 155 patients with invasive ductal carcinoma." (PMID 25011545, 2014). "In order to clarify this issue, we respectively analyzed the presence of both CD34 fibrocytes and SMA myofibroblasts in the peritumoral stroma of ductal carcinoma in situ (DCIS) and invasive ductal carcinoma (IDC)." (PMID 23469238, 2013). "To clarify this issue, we compared the distribution of CD34 fibrocytes and SMA reactive myofibroblasts between stromal areas of tumor-free mammary tissue, ductal carcinoma in situ (DCIS) and invasive ductal carcinoma (IDC)." (PMID 23469238, 2013). "In addition, a positive correlation was shown between YKL‐40 and angiogenesis markers such as CD31, CD34, and VEGFD in invasive ductal breast carcinoma, which also suggests a link between YKL‐40 and angiogenesis." (PMID 34110111, 2021). "The aim of the present study is to examine the stromal expression of CD34 and SMA in cases of invasive ductal carcinoma and to try to demonstrate the role played by the TGF-ß 1 et TGF-ß R1 pathway in the transformation of normal breast fibrocytes into myofibroblasts." (PMID 25011545, 2014). "Some authors have proposed a potential role for CD34 antigen expression as an indicator of tumor aggressiveness, noting decreased or absent CD34 positivity in the stroma of invasive ductal breast carcinomas compared with in situ ductal carcinoma or normal skin." (PMID 41597444, 2026).
lung adenocarcinoma (8 papers, 2016 to 2025). A carcinoma that arises from the lung and is characterized by the presence of malignant glandular epithelial cells. "Efficacy of RPH-120 in vivo was further tested using human lung adenocarcinoma HCC-827 cells xenografts in CD34+ humanized mice." (PMID 34456733, 2021). "We analyzed adjacent sections of paraffin embedded lung adenocarcinoma samples (n = 27) by immunohistochemistry with antibodies against CD34, CCR3 and CCR10." (PMID 27250766, 2016). "Therefore, we suggest that CD34-MVD should be routinely detected in patients with lung adenocarcinoma after operation, and the patients with low CD34-MVD should be examined and evaluated for tumor recurrence more frequently during the follow-up period." (PMID 39906069, 2025). "Therefore, the relationship between CD34-MVD and tumor progression and prognosis in patients with lung adenocarcinoma remains inconclusive and warrants further investigation." (PMID 39906069, 2025).